LEP (leptin)
Diseases named in the same sentence as LEP in open-access papers (continued):
Sharing a sentence is not in itself a finding about the gene and the disease.
Obesity (continued). "Some authors suggest that one of the most intriguing mechanisms for explaining obesity-related hyperthyrotropinemia is related to leptin, an adipocyte-derived hormone, and a key regulator of energy expenditure and food intake." (PMID 38417259, 2024). "Leptin, a hormone predominantly secreted by adipocytes, is also elevated in obesity, but its normal regulatory function on appetite and energy expenditure becomes impaired, leading to leptin resistance." (PMID 39700087, 2024). "In fact, it has been shown that subjects with obesity have higher leptin levels than subjects of the same age and gender who have a normal weight." (PMID 38172476, 2024). "Increases in BMI and leptin concentrations were associated with a modest rate of reduction in PASI score, underlining the impact of obesity and metabolic dysfunction on treatment efficacy." (PMID 39767248, 2024). "Different from ob/ob and db/db mice with the abolished leptin/LepR signaling, obese mice induced by a diet of 35% fat develop hyperleptinemia, irrespective of genotype, which are similar to most humans with obesity." (PMID 38704393, 2024). "This approach closely models leptin resistance in obesity, in which chronically high leptin concentrations contribute to a diminished response to the hormone." (PMID 39916981, 2024). "In the context of uterine function, leptin resistance has significant implications for reproductive health, particularly in individuals with obesity or metabolic disorders." (PMID 39767708, 2024). "Here, the authors demonstrate a negative feedback loop between TET2, a DNA demethylation enzyme, and leptin, an adipokine, in adipocytes, unveiling a compensatory mechanism by which the body counteracts the metabolic dysfunction induced by obesity." (PMID 38561362, 2024). "Clinically, patients with monogenic obesity present with impaired satiety and hyperphagia in early childhood with severe early-onset obesity due to dysregulation of the central leptin-melanocortin neuronal pathways." (PMID 38974580, 2024). "Various other adipokines, including leptin, adiponectin, resistin, and visfatin, are secreted by adipose tissue and are elevated in obesity, contributing to the pathophysiology of obesity-related disorders, particularly in the development of DM type 2." (PMID 39273654, 2024). "For instance, leptin, the first adipokine discovered through its role in regulating food intake, is oversecreted by adipocytes in individuals with obesity, and leptin resistance develops in the cells it targets." (PMID 38812572, 2024). "The evaluation of deletions and duplications, in regions associated with obesity, is possible by assessing genes LEPR, POMC, SIM1, LEP, MC4R, MC2R, and MC3R, and in the 16p11.2 region by MLPA." (PMID 39458556, 2024). "The most frequently occurring keywords were obesity and hypothyroidism, but also other related topics such as bariatric surgery, metabolic syndrome, insulin resistance, body mass index, and leptin." (PMID 38181287, 2024). "It has been reported that insulin and leptin signaling play a critical role in modulating glucose and lipid metabolism, and thus contribute to the development of obesity." (PMID 39000282, 2024). "It provokes the secretion of pro-inflammatory cytokines IL-6 and IL-8 in human periodontal ligament cells (hPDLCs) via binding to the obesity-related leptin and leptin receptor b (OBRb), thereby triggering subsequent intracellular signaling cascades." (PMID 39307846, 2024). "Other lower-frequency keywords, including “leptin,” “expression,” “semen,” and “overweight,” encompass the most relevant keywords for the impact of obesity on male reproductive disorders." (PMID 38299282, 2024). "We measured serum leptin levels, to eliminate the effect of obesity on leptin levels, and a leptin/BMI ratio was calculated." (PMID 38792501, 2024).
Obesity (continued). "Adipose tissue due to obesity can release several adipokines (including leptin, resistin, and adiponectin) as well as proinflammatory cytokines such as interleukin-1β, interleukin-6, and tumour necrosis factor-α." (PMID 38671417, 2024). "Mice with a pan-neuronal deletion of signal transducer and activator of transcription 3 (STAT3), the best-known transcriptional effector of leptin action, exhibit profound obesity which is similar to that seen in leptin receptor null mice." (PMID 38821928, 2024). "Hormonal activity and dietary intake can influence the regulation of leptin gene expression; i.e., leptin is downregulated in response to starvation and calorie restriction, while obesity, high-fat diets, and insulin lead to its upregulation." (PMID 39036605, 2024). "The effects of antipsychotic drugs on weight gain and obesity have been shown to include effect on the hypothalamus, antihistamine effects, sedation, decreased physical activity, and effect on leptin concentration." (PMID 38673334, 2024). "High leptin levels lead to global and/or selective leptin resistance, a condition prevalent in individuals with obesity and MetS." (PMID 39728125, 2024). "It has been shown that the concentration of leptin is higher in obese people and is proportional to the degree of obesity." (PMID 38396961, 2024). "Mutations in the leptin gene or in leptin receptor gene lead to uncontrolled food intake and early childhood obesity since leptin acts as a satiety signal." (PMID 39595074, 2024). "Leptin is a hormone produced in adipose tissue, correlated with obesity and considered a link between obesity and cardiovascular pathology." (PMID 38541144, 2024). "Several mechanisms within this context are not fully understood, and, in recent years, new strategies have been developed to restore the response to leptin in patients with obesity." (PMID 38397015, 2024). "Obesity induces leptin resistance and decreases ghrelin secretion, influencing the hypothalamus–pituitary–endocrine gland axis." (PMID 39027638, 2024). "Genes such as FTO (fat mass and obesity-associated gene), LEP (leptin), MC4R (melanocortin 4 receptor), and PPARG (peroxisome proliferator-activated receptor gamma) are well-established contributors to obesity susceptibility." (PMID 39390356, 2024). "Some related changes in obesity, like the leptin hormone, secreted by adipose tissue, can affect TRH release." (PMID 38526760, 2024). "Evaluation of the prevalence of monogenic forms of obesity in this cohort, with a special focus on leptin–proopiomelanocortin pathway abnormalities, will be investigated in the next stage of this study." (PMID 39407760, 2024). "Hypothalamic leptin resistance, a critical factor in the development of obesity and related metabolic disorders, is driven by various mechanisms, including hyperleptinemia, inflammation, endoplasmic reticulum (ER) stress, and defective autophagy." (PMID 39916981, 2024). "Leptin was initially considered for use in treating obesity; however, its altered expression and receptor expression led to Leptin resistance in obesity-related complications." (PMID 38541912, 2024). "By programming permanent hypothalamic fetal adaptations (e.g., leptin signaling), maternal obesity contributes to the intrauterine transmission of obesity by altering appetite regulation in offspring." (PMID 38613062, 2024). "Elevated levels of leptin, a hormone associated with obesity, promote glycolysis in CD8+ T cells via the PI3K/Akt/mTOR pathway, exacerbating chronic inflammation linked to obesity." (PMID 39000296, 2024). "Our results therefore show not only a reduction in the development of obesity and inflammation but also an increase in both leptin and resistin levels, and leptin resistance when using KSK-94 in animals with unlimited access to tasty food." (PMID 39065709, 2024). "This dose–response effect of leptin concentrations and obesity development can also be further described in rodent models." (PMID 38474842, 2024).
Obesity (continued). "It is suggested that obesity disrupts the balance between existing adipocytes and immune cells through adipocyte secretion of various adipokines, such as adiponectin and leptin." (PMID 39163102, 2024). "Exercise training combined with PBD is suggested as a non-invasive intervention for reducing leptin while increasing adiponectin levels to control body mass and other disorders related to obesity in adults." (PMID 39444577, 2024). "Leptin has also found to be abnormally expressed in the setting of obesity, leading to increased leptin concentrations, leptin resistance, and impaired binding to leptin receptor." (PMID 39621160, 2024). "As the concentration of IL-6 rises, there is a corresponding increase in the concentration of Leptin for patients with normal body mass, overweight, and obesity." (PMID 38786737, 2024). "In obesity, the body can resist leptin's effects, leading to an imbalance in appetite control and potential disruptions in metabolism and cardiovascular regulation." (PMID 39411599, 2024). "Leptin levels increase in obesity, and subcutaneous fat has been a major factor in determining circulating leptin levels." (PMID 38707092, 2024). "Presently, we sought to uncover the link between the changes in ovarian leptin signalling observed during obesity progression and the phenotypes of macrophages present locally." (PMID 38580672, 2024). "Physical activity, either on its own or in conjunction with changes in diet or lifestyle, can reduce the levels of leptin in individuals with prediabetes and obesity." (PMID 39444577, 2024). "According to these findings, leptin has a potential role in obesity-induced epithelial remodeling by triggering epithelial proliferation and promoting EMT." (PMID 38562155, 2024). "Alteration of leptin structure, an inability to bind to its specific receptor or leptin resistance can lead to obesity through complex and not fully understood mechanisms." (PMID 38168872, 2024). "One major hurdle is the presence of resistance in individuals with obesity, such as leptin resistance and FGF21 resistance, which reduces responsiveness to the metabolically favorable actions of these adipokines." (PMID 39872218, 2024). "Obesity and dyslipidemia were induced in mice via exposure to a high-fat diet or through Leptin gene deletion." (PMID 39234692, 2024). "The first gene to be associated with severe early-onset obesity in humans was LEP, which encodes leptin, an adipose tissue-derived hormone that regulates whole-body energy homeostasis." (PMID 39002670, 2024). "Alterations in leptin and ghrelin levels have been observed in individuals with obesity and after bariatric surgery, highlighting their importance in the physiological response to weight loss interventions." (PMID 39599699, 2024). "Visceral fat acts as an active endocrine tissue, and in patients with obesity or abnormal fat distribution, the secretion of adipose-specific cytokines (leptin, IL-6, TNF-α) is increased." (PMID 39165513, 2024). "Adipose tissue releases adipocytokines, including TNF-α, IL-6, leptin, and adiponectin, and elevated serum leptin and reduced serum adiponectin levels are characteristic features of obesity." (PMID 38542720, 2024). "Obesity is accompanied by increased serum leptin levels, which activate hypoxia-inducible factor 1-alpha (HIF-1α)-VEGF signaling in hypothalamic astrocytes, thereby inducing structural remodeling of the glial interface." (PMID 38800473, 2024). "Leptin signaling disruption in hypothalamic neurons plays a critical role in the pathogenesis of leptin resistance, which is a significant contributor to obesity and metabolic disorders." (PMID 39916981, 2024). "Conversely, thyroid function is influenced by adiposity, for example, by leptin, but also pro-inflammatory cytokines related to obesity and insulin resistance." (PMID 39408957, 2024). "Obesity is characterized by a permanent state of hyperleptinemia due to the secretion of leptin by adipose tissue." (PMID 39201522, 2024).
Obesity (continued). "Nonetheless, the regulatory factors governing hepatic LepRb expression and the potential for enhanced peripheral leptin sensitivity to overcome central leptin resistance in obesity remain poorly understood." (PMID 38623207, 2024). "Lipodystrophy and obesity represent two contrasting conditions to underscore the connection between leptin and cardiovascular health." (PMID 38702334, 2024). "Nonetheless, the higher leptin concentrations in OB humans and cats do not appear to suppress appetite, leading to the mechanism of leptin resistance (involving reduced leptin signaling or decreased transport through the blood-brain barrier) in obesity." (PMID 39328456, 2024). "The prevalence of leptin resistance in obese individuals limits its application in treatment for obesity." (PMID 39606796, 2024). "In obesity, leptin levels are elevated and act as pro-inflammatory adipokines, inducing certain cytokines such as tumor necrosis factor-alpha (TNF-α), interleukin (IL)-1, and IL-6." (PMID 38255203, 2024). "The hormone leptin has been identified as an essential nutrient during lactation for healthy metabolic programming against obesity development in adults." (PMID 38786092, 2024). "This, in essence, means that leptin plays a significant role in the insulin resistance of obesity and type 2 DM." (PMID 38707092, 2024). "Among those living with pre-pregnancy overweight or obesity, significant differences in median leptin concentrations were observed only between the adequate and excessive GWG groups." (PMID 38999894, 2024). "To explain the temporal discrepancy in the reduction of adipocyte Tet2 levels in iWAT and eWAT during obesity, we investigated the leptin levels in these two types of adipocytes." (PMID 38561362, 2024). "PTPN1 can also regulate food intake and energy expenditure by inhibiting leptin signaling in the hypothalamus, and a hypothalamus-specific loss of PTPN1 exacerbates diet-induced obesity in female mice." (PMID 38338442, 2024). "For example, the ratio of CSF leptin levels to serum leptin levels is four times greater in lean than individuals with obesity, indicating saturation of the BBB/BCB routes in these conditions." (PMID 38381398, 2024). "Blood leptin level is inversely correlated with obesity and body fat level, and exhibits a “leptin resistance” phenomenon, which is thought to play a key role in the relationship between obesity and MetS." (PMID 36656412, 2024). "Mutations of the leptin gene resulting in leptin deficiency are uncommon in humans; however, such individuals develop severe obesity with low-to-normal BP, inferring that leptin is essential for the progression of adiposity-related increased BP." (PMID 37872379, 2024). "The authors found that HIIT consisting of 30 min exercise sessions combined with citrulline (an amino acid) significantly reduced serum leptin in older adults with obesity and HIIT+ citrulline-induced effects were more profound compared to HIIT alone." (PMID 38337640, 2024). "In contrast, a smaller difference in leptin levels was observed between patients with obesity compared to BMI-matched HCs (55.0 vs 41.7 ng/mL)." (PMID 38795365, 2024). "Our data show significant differentially regulated gene enrichment in pathways related to insulin resistance and metabolic syndrome: Regulation of eIF4 and p70S6K Signaling, Insulin Secretion Signaling, PPAR Signaling, Leptin Signaling in Obesity." (PMID 38981849, 2024). "Leptin, elevated in obesity, enhances inflammation by activating macrophages and T cells, while adiponectin, an anti-inflammatory adipokine, is reduced in obesity." (PMID 39731011, 2024). "Intriguingly, a pharmacological bolus of fluorescently labeled leptin equally accumulates in the CVOs and choroid plexus of lean versus obese mice, against the idea that impaired brain leptin access in obesity contributes to leptin resistance." (PMID 38381398, 2024).
Obesity (continued). "Previous work has revealed that leptin sensitivity can be restored in hyperleptinemic obesity by inhibiting leptin." (PMID 39872508, 2024). "In this sense, knowledge of the pathophysiology of obesity-related illnesses and the role that leptin plays in regulating energy balance should lead to the development of novel therapeutic options for obesity." (PMID 39125635, 2024). "Leptin, an adipokine with a crucial role in metabolism, obesity, and cardiovascular diseases, has also been found to activate macrophages and T-lymphocytes, stimulating their cytokine secretion." (PMID 38397476, 2024). "Future research should focus on longitudinal and intervention studies to establish causal relationships between dietary fat consumption, inflammatory markers, and leptin levels in obesity." (PMID 39700087, 2024). "Serum leptin levels are usually undetectable and clinically heterozygous patients are characterized by early-onset obesity, whereas in a homozygous state, hypogonadotropic hypogonadism and hypothyroidism can also be seen." (PMID 38397265, 2024). "LEP has been proposed as a biomarker of sleep disorders given that it acts as a mediating factor between obesity and poor sleep." (PMID 39194505, 2024). "In this review, we focus on the role of the adipokine leptin, whose blood concentration is greatly elevated in proportion to patient obesity." (PMID 39439572, 2024). "The role of these populations in leptin signalling has also been evaluated and, whereas a knockout of the LepR in AGRP/NPY neurons of adult mice causes extreme obesity, deletion of the LepR from adult POMC neurons has only a minimal effect." (PMID 39478220, 2024). "Leptin is produced by adipose tissue and is sometimes considered the “anti-obesity” hormone due to its role in regulating energy balance and suppressing appetite." (PMID 39621160, 2024). "Periodontal infection had little effect on obesity parameters such as serum leptin levels and liver weight." (PMID 39553478, 2024). "An increase in obesity is correlated with elevated levels of leptin, a hormone that stimulates the release of luteinizing hormone (LH) via hypothalamic gonadotropin-releasing hormone (GnRH) neurons." (PMID 39722803, 2024). "Leptin concentration is regulated by food intake and correlates with fat tissue mass, hence hyperleptinemia is observed in obesity." (PMID 39065709, 2024). "Our study concentrated on some of the most vital obesity stress markers, such as leptin and IL-6, which represent crucial facets of the intricate obesity-associated stress network." (PMID 38178093, 2024). "A role seems to be played by the decreased levels of adiponectin and the increased secretion of proinflammatory adipo-cytokines such as leptin, resistin and IL-6 in males with obesity." (PMID 38765954, 2024). "The pathogenesis of obesity involves various mechanisms, including the leptin-melanocortin signaling pathway, genes related to energy homeostasis in neuron development, and syndromic obesity associated with ciliopathies." (PMID 38674329, 2024). "Between IL-6 and Leptin concentrations, a positive average correlation is observed for patients with normal body mass, overweight, and obesity (Pearson: 0.51, p = 0.006)." (PMID 38786737, 2024). "The dysregulation of leptin signaling contributes to the pathogenesis of obesity and metabolic disorders." (PMID 38255203, 2024). "Leptin is involved in low-grade inflammation due to overweight and obesity and is considered a proinflammatory adipokine." (PMID 38610754, 2024). "Leptin has been under investigation as a treatment option for obesity, further helping dyslipidemia and reducing the risks for atherosclerosis and other cardiovascular diseases." (PMID 38892018, 2024). "A novel mechanism of endothelial dysfunction and cardiac fibrosis in obesity is leptin-mediated aldosterone production, which impairs myocardial relaxation and contributes to CVD." (PMID 38397015, 2024).